PGRMC1 (progesterone receptor membrane component 1)
Diseases named in the same sentence as PGRMC1 in open-access papers (continued):
Sharing a sentence is not in itself a finding about the gene and the disease.
breast carcinoma (continued). "Our work was inspired by the discovery that PGRMC1 phosphorylation differs between breast cancer subtypes differing in estrogen receptor expression, that also exhibit starkly contrasting levels of patient survival." (PMID 32293262, 2020). "PGRMC1 has been shown to be increased in breast cancer cell lines and breast tumor tissue, however the mechanism behind its role in breast cancers remains elusive." (PMID 32867363, 2020). "Further, significant alterations in cell-cycle progression were observed after PGRMC1 silencing, as cell cycle in both breast cancer cell lines was arrested in the G1 phase." (PMID 32704174, 2020). "PGRMC1 overexpression was further validated by analysing a panel of proprietary normal breast and breast cancer cell lines, which revealed high mRNA and protein levels of PGRMC1 in both ER-positive ZR-75-1 and TNBC MDA-MB-468 cell lines." (PMID 32704174, 2020). "Our findings advert to a complex and diverse impact of PGRMC1 on lipid homeostasis in breast cancer." (PMID 32660617, 2020). "To show the increasing effect of PGRMC1 on expression of enzymes of the lipid metabolism, we obtained normalized microarray data of 63 hormone receptor-positive breast cancers tissue samples." (PMID 32660617, 2020). "For this purpose, multiple breast cancer cells were screened for PGRMC1 expression, which was analysed using online RNAseq-based gene expression from non-malignant and malignant breast cell lines (Breast Cancer Cell Lines-Heiser 2012 dataset)." (PMID 32704174, 2020). "PGRMC1 also influenced lipid raft formation leading to altered expression of growth receptors in membranes of breast cancer cells." (PMID 32660617, 2020). "The impact of PGRMC1 on breast cancer growth and progression was studied following chemical inhibition and alteration of PGRMC1 expression, and evaluated by using online-based gene expression datasets of human breast cancer tissue." (PMID 32704174, 2020). "It is worth mentioning that the role of PGRMC1 is mainly evidenced in the luminal type A breast cancer cell lines (MCF7 and T47-D); meanwhile, MDA-MB-231 cell proliferation remains unaltered, even when PGRMC1 expression is artificially altered." (PMID 33076541, 2020). "Non-classical signaling can also contribute to breast cancer pathology; studies have demonstrated an up regulation of mPRα and PGRMC1 in breast cancer cell lines." (PMID 32867363, 2020). "The aim of our study was to investigate the involvement of PGRMC1 in cholesterol metabolism to detect new mechanisms by which PGRMC1 can increase lipid metabolism and alter cancer-related signaling pathways leading to breast cancer progression." (PMID 32660617, 2020). "Once high PGRMC1 expression in breast cancers was established, the investigation shifted towards elucidating the mechanisms behind this phenomenon." (PMID 32704174, 2020). "Gene ontology (GO) term enrichment pathway analysis by REACTOME revealed alterations to important signalling mechanisms following AG-205 treatment or PGRMC1 silencing of both breast cancer cell lines." (PMID 32704174, 2020). "Increased expression of the progesterone receptor membrane component 1 (PGRMC1) has been linked to multiple cancers, including breast cancer." (PMID 32704174, 2020). "Our analysis revealed PGRMC1 to be widely expressed throughout multiple subtypes of breast cancer cells and tissues." (PMID 32704174, 2020). "Our results thus enhance the current understanding of PGRMC1 downstream signalling and broaden the current knowledge of the role of PGRMC1 signalling network in inducing breast cancer cell growth." (PMID 32704174, 2020).
breast carcinoma (continued). "Although previous studies report on the proliferative effect of PGRMC1 in breast cancer, little is known about the mechanisms by which PGRMC1 effects carcinogenesis." (PMID 32660617, 2020). "Silencing PGRMC1 also impaired the migratory and invasive capabilities of both breast cancer cell lines." (PMID 32704174, 2020). "We demonstrate that PGRMC1 mediates progression of breast cancer cells potentially by altering cholesterol and lipid metabolism and activating key drivers of tumor progression in breast cancer, namely ERα expression and activation, as well as EGFR signaling." (PMID 32660617, 2020). "Levels of molecular markers associated with cell-cycle progression, CDK4 and Cyclin D1, also decreased following PGRMC1 silencing, whereas the expression of pro-apoptotic markers, Bax and cleaved-caspase 3, increased in both breast cancer cell lines." (PMID 32704174, 2020). "In our present study, we focused on this regulating influence and its possible involvement in PGRMC1-induced breast cancer promotion." (PMID 32660617, 2020). "TCP1 (P17987) expression is driven by oncogenic PI3K signaling in breast cancer, and we observe both elevated PGRMC1-dependent PI3K/AKT activity and TRiC abundance in DM cells." (PMID 32245408, 2020). "Pgrmc1 co-immunoprecipitates with mPRα, and manipulation of Pgrmc1 expression with siRNA or mRNA transfection alters the plasma membrane localization of mPRα in breast cancer cells and in zebrafish oocytes resulting in alterations in mPRα functions." (PMID 30319543, 2018). "It further suggests an important role of PGRMC1 in the tumorigenesis and progression of breast cancer in progestin-based hormone replacement therapy." (PMID 29069804, 2017). "We report that treatment of both breast cancer cell lines with the progestin norethisterone (NET) induces phosphorylation of PGRMC1 at the Casein Kinase 2 (CK2) phosphorylation site Ser181, which can be decreased by treatment with CK2 inhibitor quinalizarin." (PMID 29069804, 2017). "We demonstrated that overexpression of PGRMC1 in MCF7 breast cancer cells (MCF7/PGRMC1) results in increased proliferation upon progestin treatment, as compared to empty vector control cells (MCF7/EVC)." (PMID 29069804, 2017). "In previous studies, we have shown that PGRMC1 is involved in the mode of action of progestins on breast cancer cells." (PMID 29069804, 2017). "Over recent years, we have investigated the impact of progestins on breast cancer, indicating a role of PGRMC1 in the signaling cascade after binding of progestins to hormone receptors." (PMID 29069804, 2017). "Human breast cancer cells (MCF-7) served as positive control for establishing the immunohistochemical staining for PGRMC1, PAIRBP1, and PAQR7." (PMID 27340667, 2016). "PGRMC1 has an established role in progesterone signaling, and in some diseases, such as breast cancer, this contributes to hormonal growth and anti-apoptotic signaling." (PMID 27867772, 2015). "Phosphatase treatment of primary breast cancer proteins demonstrated that these different isoforms of PGRMC1 differed at least partly in their phosphorylation status." (PMID 18922159, 2008). "Immune fluorescence using anti-PGRMC1 monoclonal antibody 5G7 was performed on breast cancer tissue microarrays." (PMID 18922159, 2008). "Taken together, these data are consistent with differences in the phosphorylation status of PGRMC1 observed in breast cancers, potentially being able to influence the clinically relevant survival phenotype of those cancers." (PMID 18922159, 2008). "Simultaneous mutation of PGRMC1 serine-56 and serine-181 fully abrogated the sensitivity of stably transfected MCF7 breast cancer cells to peroxide-induced cell death." (PMID 18922159, 2008). "PGRMC1 is overexpressed in human breast cancers of the basal subtype using PAM50 (P = 4 × 10−30)." (PMID 39804138, 2025). "Similar findings were observed in PGRMC1-deplete ovarian and breast cancer xenograft tumors." (PMID 40227710, 2025).
breast carcinoma (continued). "PGRMC1 is an enigmatic heme-binding protein, is highly expressed in breast cancer tissue, and may be important in tumorigenesis." (PMID 38322112, 2024). "As PGRMC1 overexpression in breast cancer cells leads to higher E2 secretion, T-HESCs E2 production might depend on PGRMC1 activation." (PMID 38308254, 2024). "Another in vitro study revealed that the created Asp120Gly PGRMC1 mutant did not bind heme and caused increased susceptibility of breast cancer cells to doxorubicin and camptothecin, two topoisomerase inhibitors used as chemotherapeutic agents." (PMID 38804287, 2024). "Membrane-associated-progestin-and-adipoQ-receptors (mPRs/PAQR5-9) activate JNK1/2 and p38 MAPKs to elicit apoptosis in ovarian cancer cells, and progesterone receptor membrane component 1 (PGRMC1) augments breast cancer growth via transactivation of EGFR-PI3K-AKT signaling." (PMID 37686465, 2023). "In a previous study using xenograft models, PGRMC1 depletion in MCF7 and T47D cells resulted in suppression of tumor growth; as both MCF7 and T47D cells belong to the luminal A subtype, PGRMC1 was suggested to regulate the growth of breast cancer via ER signaling." (PMID 33832499, 2021). "PGRMC1 knockdown resulted in a significantly reduced migration rate in breast cancer cell lines." (PMID 33832499, 2021). "Furthermore, the upregulated expression of PGRMC1 in breast cancer patients was also confirmed at protein level." (PMID 34746100, 2021). "Here, we provide evidence that crosstalk exists between PGRMC1 and ERα that could promote progression of breast cancer." (PMID 34830790, 2021). "PGRMC1 showed a significant role in the migration of breast cancer cells, and may serve as a potential therapeutic target in breast cancer." (PMID 33832499, 2021). "NF-κB signaling is a major contributor that links inflammation to HCC; moreover, considering its potential relevance with Pgrmc1 in lung adenocarcinoma and breast cancer, further targeted studies are needed in order to determine how Pgrmc1 modulates the NF-κB complex in other pathological settings." (PMID 34069911, 2021). "Progesterone receptor membrane component 1 (Pgrmc1) is a non-classical progesterone receptor associated with the development of the mammary gland and xenograft-induced breast cancer." (PMID 33832499, 2021). "Considering that PGRMC1 is expressed in breast tissue and overexpressed in breast cancer, further investigation of progestin-dependent PGRMC1 signaling in breast cancer cells is essential for a better understanding of the effects of progestins on breast cancer risk." (PMID 34830790, 2021). "Moreover, previous studies reported that the E2/NET combination enhanced the proliferation of PGRMC1-overexpressing breast cancer cells, both in vivo and in vitro." (PMID 34779589, 2021). "PGRMC1 may regulate the proliferation and progression of breast cancer cells, potentially by altering lipid metabolism and by activating key oncogenic signaling pathways, such as ERα expression and activation, as well as EGFR signaling." (PMID 34746100, 2021). "Another possible mediator of the effect of PGRMC1 on breast cancer migration is MMP9, which promotes the colonization of the lungs by inducing metastatic aggressiveness as well as the migration and invasion of cancer cells while not significantly affecting the tumor burden." (PMID 33832499, 2021). "Furthermore, considering the recent evidence suggesting that the blood level of PGRMC1 is a potent marker for breast cancer prognosis, our study also shows the possibility of using Pgrmc1 as a survival expectancy marker in patients with breast cancer." (PMID 33832499, 2021). "Likewise, it was demonstrated that Pgrmc1 positively regulates tumorigenic features of breast cancer cells through the EGFR signaling pathway." (PMID 34069911, 2021).
breast carcinoma (continued). "This study emphasizes the role of PGRMC1 in a key breast cancer signaling pathway which may provide a new avenue to target hormone-dependent breast cancer." (PMID 34830790, 2021). "PGRMC1 a member of the membrane-associated progesterone receptor (MAPR) family with the ability to initiate non-classical signaling has been described in breast cancers." (PMID 34350123, 2021). "Thus, our data demonstrates that therapeutic targeting of PGRMC1 in aggressive breast cancers leads to the activation of miRNAs that target overexpressed genes and deactivation of miRNAs that have oncogenic potential." (PMID 34350123, 2021). "Since activated PGRMC1 may potentiate the oncogenic signaling of ERα and thereby promote breast cancer progression, it may serve as a therapeutic target." (PMID 34830790, 2021). "Considering that PGRMC1 was shown to be correlated with the ER status in breast cancer, PGRMC1 may have a role in the regulation of the progression of luminal A and luminal B subtypes of breast cancer." (PMID 33832499, 2021). "Our data rather describes the impact of PGRMC1 on PHBs’ function as transcription factor modulators and contributes to revealing the PGRMC1 regulatory network with special focus on processes driving breast cancer progression." (PMID 34830790, 2021). "The suppressive ability of PGRMC1 inhibition on tumor cell migration and metastasis is of potential clinical importance considering the critically high mortality rate of metastasis in breast cancer." (PMID 33832499, 2021). "However, tumor-bearing Pgrmc1 KO mice showed a significantly longer survival duration (p = 0.0065) compared with tumor-bearing WT mice, suggesting that Pgrmc1 is related to the aggravation of the disease course of breast cancer." (PMID 33832499, 2021). "PGRMC1 mRNA expression and survival in breast cancer were analyzed." (PMID 34746100, 2021). "Besides heme binding with PGRMC1, recent report shows that PGRMC1 Y113 residue, which is essential for heme binding, is phosphorylated in breast cancer MCF7 cells." (PMID 34209885, 2021). "PGRMC1 is thereby involved in a key oncogenic signaling pathway in breast cancer." (PMID 34830790, 2021). "We found that PGRMC1 was overexpressed in human breast cancer." (PMID 34746100, 2021). "To determine whether Pgrmc1 is involved in the induction of breast cancer, we first investigated the incidence of breast cancer in PyMT wild-type (WT) and PyMT Pgrmc1 KO mice and their survival duration." (PMID 33832499, 2021). "Therefore, the aim of this study was to gain deeper insight into PGRMC1-mediated breast cancer progression upon progestin treatment and the signaling pathways involved." (PMID 34830790, 2021). "Interestingly, increased AG-205 concentration yielded minimal alterations in PGRMC1 protein levels in both breast cancer cell lines." (PMID 32704174, 2020). "PGRMC1 has the potential to be a viable biomarker for clinical diagnosis of breast cancers." (PMID 32867363, 2020). "Immunohistochemistry, immunofluorescence along with machine learning and staining intensity software could be used to identify PGRMC1 in human breast cancer tissues." (PMID 32867363, 2020). "Our work thus provides evidence indicating that PGRMC1 could be a potential oncogene, as it has the capacity for regulating cell survival pathways in breast cancers." (PMID 32704174, 2020). "We, therefore, posit that PGRMC1 plays a crucial role in breast cancers, and could potentially serve as a target for both ER-positive and TNBC cells." (PMID 32704174, 2020). "PGRMC1 has been confirmed to play a role in carcinogenesis especially in breast cancer and may therefore represent a target for cancer therapy." (PMID 32660617, 2020). "Similarly, enhanced PGRMC1 expression was detected in other breast cancer cell types—the luminal A type MCF7 and triple-negative BT-20 (p < 0.01 and p < 0.001, respectively)." (PMID 33076541, 2020).
breast carcinoma (continued). "PGRMC1 may mediate proliferation and progression of breast cancer cells potentially by altering lipid metabolism and by activating key oncogenic signaling pathways, such as ERα expression and activation, as well as EGFR signaling." (PMID 32660617, 2020). "We thus posit that PGRMC1 overexpression in breast cancer cells could promote cell survival by interacting with EGFR in the cell membrane." (PMID 32704174, 2020). "Normal MCF10A breast cells, as well as ZR-75-1 and MDA-MB-468 breast cancer cells, were treated with a selective PGRMC1 inhibitor (AG-205) at different concentrations (10–100 μM) for 24 h to determine the optimal dose for studying the PGRMC1 mechanism of action." (PMID 32704174, 2020). "PGRMC1 also interacts with progestin to mediate proliferative effects in breast cancer cells." (PMID 28107520, 2017). "Considering that PGRMC1 is expressed in breast tissue and overexpressed in breast cancer, further investigation of PGRMC1 activation and the resulting response of breast cancer cells is essential for the better understanding of the effects of progestins on breast cancer risk." (PMID 29069804, 2017). "It again demonstrates a role of PGRMC1 in transducing progestin signals in breast cancer cells." (PMID 29069804, 2017). "In some diseases, PGRMC1 expression correlates with poor patient survival, while in breast cancer, the correlation between PGRMC1 and survival is more complex and may depend on the patient population or epitopes being analyzed." (PMID 27867772, 2015). "This antibody recognized endogenous PGRMC1 in breast cancer tissues." (PMID 18922159, 2008). "PGRMC1, which had not previously been directly associated with ER-α status in breast cancer, was detected in three separate spots." (PMID 18922159, 2008). "Future research should address what role, if any, these proposed interactions of PGRMC1 with those candidate interaction partners may play in breast cancer." (PMID 18922159, 2008). "PGRMC1 may be related to both breast cancer proliferation and cholesterol transport." (PMID 39804138, 2025). "Furthermore, we demonstrate that PGRMC1 and TMEM97 expression are associated with an increased risk of tumor recurrence within the first 5 years following breast cancer diagnosis, in a manner that seems to be mediated by their association with cellular proliferation." (PMID 39804138, 2025). "This is supported by recent findings in breast cancer cell lines that different synthetic progestins cause many of the same cellular outcomes when signaling through the classical or nuclear progesterone receptor (PGR), but have seemingly distinct PGRMC1-dependent actions." (PMID 34885064, 2021). "Additionally, both in vivo and in vitro investigations have been demonstrated that combination therapy with estradiol and estrogen/norethisterone increases the overexpression of proliferation of progesterone receptor membrane component 1 in breast cancer cells." (PMID 34698654, 2021). "Lastly, EMT may also be involved in the PGRMC1-induced migration of breast cancer cells." (PMID 33832499, 2021). "Whether the genetic deletion of Pgrmc1 affects the progression of breast cancer is still unclear." (PMID 33832499, 2021). "Since the initial results point towards progestin-dependent increase of proliferation in ERα/PR-positive PGRMC1-overexpressing cell lines, we hypothesized that progestin-mediated PGRMC1 signaling is dependent on factors present in luminal cell types of breast cancer." (PMID 34830790, 2021). "Furthermore, it is still unclear whether metastasis of breast cancers can be influenced by the levels of PGRMC1 protein." (PMID 33832499, 2021). "Indeed, PGRMC1 might also reduce viability of breast cancer cells under treatment with statins, because PGRMC1 is known to interact with CYP enzymes." (PMID 32660617, 2020).